BRCA2 (BRCA2 DNA repair associated)
Diseases named in the same sentence as BRCA2 in open-access papers (continued):
Sharing a sentence is not in itself a finding about the gene and the disease.
breast cancer (continued). "Until further investigation can be completed into the specific impact of frequent and rare APC and BRCA2 variants in Arab cohorts, all patients carrying either APC or BRCA2 variants should be considered at elevated risk of CRC and breast cancer and be offered screening accordingly." (PMID 37306523, 2023). "The c.6410del BRCA2 genetic alteration has previously been mentioned in two publications as a variant associated with increased risk of developing breast cancer, however, there were no publications regarding its association with GC." (PMID 37623222, 2023). "In contrast with these data, a large retrospective study from the Breast Cancer Linkage Consortium documented an increased risk of EC in BRCA1-mutated women but not in BRCA2-mutated women." (PMID 36837501, 2023). "Reduced BRCA2 expression in canines is related to the development of mammary tumors." (PMID 36851449, 2023). "The combined results from the two studies strongly indicate a low frequency of BRCAness among non-BRCA1/BRCA2 familial breast cancer patients with no identified variants in other HRD genes." (PMID 37316882, 2023). "Of the 19 persons with cancer carrying BRCA2 variants, eight had breast cancer, seven of which lacked BRCA1 variants." (PMID 37306523, 2023). "Unlike BRCA1-associated cancers, BRCA2 tumours often express estrogen and progesterone receptors with similar features as sporadic breast cancers." (PMID 36980802, 2023). "Height was a risk factor for premenopausal breast cancer in BRCA2 variant carriers, but not BRCA1 carriers." (PMID 37340476, 2023). "T. gondii infection decreased CCND1 expression and increased BRCA2 expression, which suggests that T. gondii infection could suppress breast cancer growth." (PMID 36341349, 2022). "Breast cancer is the most common neoplasia in females worldwide, about 10% being hereditary/familial and due to DNA variants in cancer-predisposing genes, such as the highly penetrant BRCA1/BRCA2 genes." (PMID 36035419, 2022). "Interestingly, defect in the HRR pathway in patients with sporadic breast cancer can mimic the phenotype of familial BRCA1 and BRCA2 mutation carriers which is termed as BRCAness." (PMID 35715772, 2022). "The patients with BRCA1 mutation had the worst survival in both breast cancer and ovarian cancer, compared to the patients with BRCA2 mutation and patients with no mutations." (PMID 35205313, 2022). "However, other contributing factors for this association need to be investigated such as defects in homologous recombination (e.g., BRCA1, BRCA2, PALB2, ATM, CHEK2) known to increase risk of breast cancer." (PMID 36421330, 2022). "Indeed, PARP1 inhibitors are currently one of the most promising therapeutic agents for several cancers, especially breast cancer, and can selectively target tumor cells with BRCA1 or BRCA2 tumor suppressor gene mutations through synthetic lethality." (PMID 36266635, 2022). "Notably, hereditary breast cancer is often associated with mutations in tumor suppressor BRCA1 and BRCA2 genes." (PMID 36139526, 2022). "In addition, there are no prospective trials comparing different cancer risk–reducing strategies in patients with breast cancer that tested positive for the BRCA1 and BRCA2 pathogenic variants who were treated with BCT at the first event." (PMID 36580360, 2022). "Lifetime breast cancer risk is up to 1.2% in male BRCA1 carriers and up to 8.8% in BRCA2 carriers, compared to 0.1% in the general population; the lifetime prostate cancer risk is higher in BRCA2 than BRCA1 carriers and the general population, specifically up to 20–25%." (PMID 35448177, 2022). "Many breast cancer patients who had a higher inherited risk of developing the disease tested negative for BRCA1 or BRCA2 P/LP-Vs, necessitating additional genetic testing using larger gene panels." (PMID 36140642, 2022).
breast cancer (continued). "In our sample, we had a higher percentage of BRCA2 mutation carriers; this result is interesting, since usually, BRCA1 shows a higher incidence compared to BRCA2, with a lifetime risk of developing breast cancer of 65% for BRCA1 mutation carriers and of 40% in patients with BRCA 2 mutation." (PMID 35573021, 2022). "An example of this is PARP inhibitors, which have been approved for breast cancers in both the metastatic and the early-stage setting for patients with germline pathogenic BRCA1 or BRCA2 mutations, and for ovarian, pancreatic, and prostate cancers with BRCA1 or BRCA2 mutations." (PMID 35703177, 2022). "This translates to a reduction in ovarian cancer-specific mortality between 80–96% and in breast cancer-specific mortality of 42%, which is more pronounced for BRCA1 (HR 0.45, p < 0.0001) vs. BRCA2 mutation carriers for whom the reduction loses significance (HR 0.88, p = 0.75)." (PMID 35267543, 2022). "In this study, we built a new model (ARiCa: Asian Risk Calculator) for estimating the likelihood of carrying a pathogenic variant in BRCA1 or BRCA2 gene, using germline BRCA genetic testing results in a cross-sectional population-based study of 8,162 Asian breast cancer patients." (PMID 35143328, 2022). "The study demonstrated that TNBC was closely related to BRCA1 mutations, compared to patients with BRCA2 mutations carriers or non-carriers, breast cancer patients with BRCA1 mutation are more likely to have TNBC." (PMID 36242046, 2022). "It is also possible that inherited rare mutations implicating in breast cancer risk, such as BRCA1 and BRCA2 germline mutations, could explain part of the variance in the MRSs." (PMID 35681745, 2022). "HBOC is caused by pathogenic variants in BRCA1/2 which confer substantially elevated risks for female breast cancer, ovarian cancer, and male breast cancer (in particular for BRCA2 carriers), in addition to increased risks for pancreatic cancer, prostate cancer, and melanoma." (PMID 36353115, 2022). "The cancer genome panel identified mutations in AT-rich interaction domain 1A(ARID1A)and breast cancer susceptibility gene 2 (BRCA2), but there were no available clinical trials or recommended drugs." (PMID 36426335, 2022). "Our study also found that 12 (9.8%) BBC patients carried BRCA2 deleterious variants, higher than eight (6.5%) identified with BRCA1 deleterious variants, which was similar to other Chinese studies that evaluated unselected breast cancer patients." (PMID 36324133, 2022). "This study included 2346 women, 1844 of whom had a mutation in the BRCA1 gene and 502 in the BRCA2 gene, all without breast cancer." (PMID 35805026, 2022). "There have been very few genetic studies on pre-disposition to mammary tumours in cats, with the focus having been to look for the presence of germline mutations in BRCA1 and BRCA2, as the cumulative breast cancer risk in humans is 72% for BRCA1 and 69% for BRCA2 carriers." (PMID 36288160, 2022). "Putative duplications overlapping the breast cancer tumour suppressor gene STK11 suggested decreased risk of breast cancer in our study for both BRCA1 carriers (HR = 0.49, 95%CI 0.29–0.81, p = 5.4 × 10−3) and BRCA2 carriers (HR = 0.44, 95%CI 0.22–0.88, p = 9.2 × 10−3)." (PMID 36203093, 2022). "The AUC for the artificial neural network model was 0.903 (95% C.I. = 0.836–0.949, 0.858 for BRCA1 and 0.855 for BRCA2), while the AUC for nomogram predicting the risk of BRCA1/2 germline deleterious mutation in Chinese bilateral breast cancer patients was 0.828 (95% C.I. = 0.750–0.890)." (PMID 36324133, 2022).
breast cancer (continued). "Indeed, approximately 40% of inherited cancers are due to mutations in the breast cancer susceptibility genes 1 and 2 (BRCA1 and BRCA2)." (PMID 35406503, 2022). "Its absence in Icelander general population highlights the possibility that BRCA2 c.771_775del (999del5) may have lower prevalence in Icelander general population but be enriched in Icelander breast cancer cohort." (PMID 35595529, 2022). "The most common gene mutations associated with breast cancer are BRCA1 and BRCA2 mutations." (PMID 37435457, 2022). "The approximate risk of breast cancer is 65–79% with BRCA1 PV and 61–77% for BRCA2 PV11." (PMID 35469032, 2022). "However, most carriers of BRCA1 and BRCA2 with TN breast cancer in stage I benefited from RRBM-RRBSO or just RRBSO." (PMID 36580360, 2022). "Women who have an increased risk of developing breast cancer due to mutations in cancer susceptibility genes (i.e., BRCA1, BRCA2, PALB2, ATM, and CHEK2) or a familial predisposition undergo adapted screening programs compared to women who are at population risk." (PMID 36293255, 2022). "Although BRCA2 c.771_775del (999del5) is the major founder mutation in Icelander breast cancer, it was not present in the 27 DDR deleterious variants identified in the Icelander population of 12,584 individuals included in our study." (PMID 35595529, 2022). "In addition to OC, RRBSO is associated with a 40–70% reduced risk of breast cancer in the BRCA 1/2 mutation carrier population, with effects particularly in premenopausal BRCA2 carriers, but more recently in both BRCA 1/2." (PMID 35323372, 2022). "This “LOH reversal” was observed in two BRCA2 mutation carriers with breast cancer, treated with non-platinum chemotherapy and radiation, and two BRCA1 mutation carriers with ovarian cancer, both treated with platinums." (PMID 36344544, 2022). "This retrospective study demonstrated that the reversion mutations were observed in three HRR-associated genes (BRCA1, BRCA2 and PALB2) with four cancer types (breast cancer, pancreatic cancer, ovarian cancer, and lung cancer) from this Chinese pan-cancer patient cohort." (PMID 35281878, 2022). "The most notable mutations in breast cancer occur in the BRCA1 and BRCA2 genes." (PMID 35764927, 2022). "BRCA1 or BRCA2 mutations are associated with high penetrance rates; the estimated mean cumulative risks for breast cancer by age 70 years for BRCA1 and BRCA2 mutation carriers, as reported by a meta-analysis, were 57% (95% CI, 47% to 66%) and 49% (95% CI, 40% to 57%), respectively." (PMID 35402282, 2022). "Whether exogenous estrogens, such as oral contraceptives, modify the breast cancer risk in BRCA1 and BRCA2 mutation carriers is actually a controversial topic." (PMID 36230696, 2022). "It is known that carriers of BRCA1 PVs tend to develop ER-/PR-/HER2-, i.e. triple negative breast cancers (TNBC), while carriers of BRCA2 PVs tend to develop ER + /PR + breast cancers, similar to sporadic forms lacking germline predispositions." (PMID 35135604, 2022). "Considering that PARP inhibitors can elicit cell death in BRCA1 or BRCA2 mutant breast cancer cells, we speculated that LCS-1 may induce cell death via degrading PARP and BRCA1." (PMID 35978820, 2022).
breast cancer (continued). "Two primary risk factors of breast cancer development are mutations in the BRCA1 and BRCA2 genes, which can be linked to a family history of breast cancer, as well as the use of hormone-replacement therapy that causes extended exposure to female hormones, such as estrogen." (PMID 36012771, 2022). "Dosing this panel of antigens (OVALife test) provides a reliable screen of patients at high risk, such as women younger than 50 years old with positive familiarity for ovarian or breast cancer, particularly if they bear a BRCA1 or BRCA2 gene mutation or belong to families with Lynch 2 syndrome." (PMID 35954427, 2022). "There are DNA-damaging agents that regulate BRCA2 promoter activity in breast cancer cell lines." (PMID 35740092, 2022). "Their cumulative risk of breast cancer (BC) may be as high as 70% for carriers of both genes, whereas the risk of ovarian cancer (OC) is estimated to be 44% for BRCA1 carriers and 17% for BRCA2 carriers." (PMID 35123550, 2022). "• miR-34a correlates directly with breast-cancer susceptibility genes BRCA1, and BRCA2." (PMID 37303494, 2022). "Assessing the HRs for CNV versus non-CNV pathogenic variants, separately for BRCA1 and BRCA2 suggested elevated breast cancer risk for BRCA1 deletions (HR = 1.21, 95%CI = 1.09–1.35) but not BRCA2 deletions." (PMID 36203093, 2022). "Similarly, in our simulation model patients with TN breast cancer aged under 40 years with the BRCA1 and BRCA2 pathogenic variants in stage I/II who received adjuvant chemotherapy had no survival benefit from RRBM." (PMID 36580360, 2022). "In breast cancer patients with germline pathogenic BRCA1/2 mutations, cancer cells harbor homologous recombination repair deficiency (HRD) due to malfunction of BRCA1 or BRCA2 protein in DNA damage repair." (PMID 35855837, 2022). "Breast cancer-associated genes 1 and 2 (BRCA1 and BRCA2) are tumor suppressor genes encoding a large protein that is involved in many essential biological processes, including DNA damage repair, cell cycle checkpoints, chromatin remodeling, transcriptional regulation, and protein ubiquitination." (PMID 35573021, 2022). "The risk is also relatively higher than in men with first-degree relatives and those with breast cancer gene mutation 2 (BRCA2) rather than breast cancer gene mutation 1 (BRCA1)." (PMID 36686127, 2022). "Given the propensity for triple‐negative breast cancer with BRCA1 mutations, as anticipated, most of the identified mutations were in BRCA2; therefore, the findings may be less applicable to BRCA1‐associated breast cancers." (PMID 35128817, 2022). "The aim of the study is to compare the outcomes of implant and synthetic TIGR mesh-based breast reconstructions in breast cancer patients and women, who have higher lifetime risk for breast cancer, with mutated (changed) copy of genes: BRCA1, BRCA2, PALB2 or CHEK2." (PMID 35804960, 2022). "In addition, BRCA1/BRCA2 MINAS women were significantly more likely than BRCA1 or BRCA2 women to have had breast cancer." (PMID 34983940, 2022). "Background and Objectives: BRCA 1 and 2 mutations have a cumulative risk of developing ovarian cancer at 70 years of 41% and 15%, respectively, while a cumulative risk of breast cancer by 80 years of age was 72% for BRCA1 mutation carriers and 69% for BRCA2 mutation carriers." (PMID 35888662, 2022). "Currently, approximately 40% of familial breast cancer risk is explained by a combination of common low-penetrance variants, together with coding rarer variants in predisposition genes, such as BRCA1, BRCA2, PALB2, ATM, and CHEK2 that confer higher risks." (PMID 35884425, 2022). "Kristiansen and colleagues investigated the XCI in breast cancer, revealing a higher frequency of skewed XCI in women aged 27 to 45 years compared to matched controls, while the likelihood of carrying the BRCA1 or BRCA2 mutation is unrelated to the XCI pattern." (PMID 35456502, 2022).
breast cancer (continued). "However, these variants are too rare in the general population to explain more than a small proportion of breast cancer cases, especially among Chinese women where the prevalence of BRCA1 and BRCA2 mutations is lower than that in women of European ancestry." (PMID 35395775, 2022). "Thus, the application of a PARP1 inhibitor with RT leads to greater inhibition in BRCA2− than BRCA2+ breast cancers." (PMID 35643812, 2022). "This lack of diversity in trials to test targeted therapies has important implications for breast cancer disparities given the marked variation in the prevalence of certain mutations of high-penetrance genes, such as BRCA1 and BRCA2, and breast tumor subtypes across racial and ethnic populations." (PMID 35151316, 2022). "The random-effects meta-analysis in BRCA2 mutation carriers showed a slight, non-significant reduction in the risk of breast cancer: OR = 0.98, 95% CI: 0.62 to1.55, p = 0,9243." (PMID 36230696, 2022). "Interestingly, the relationship between iNOS expression and the expression of breast cancer protooncogenes HER2, BRCA1, and BRCA2 in the pathogenesis of breast cancer is not well understood." (PMID 35740092, 2022). "Telli and colleagues present a phase II clinical trial of the PARP inhibitor talazoparib in patients with solid tumors and show that the drug has activity in patients with breast cancer with mutations in other homologous recombination pathway genes beyond BRCA1 and BRCA2." (PMID 36253484, 2022). "Studies have shown that BRCA1 P/LP variant positive patients present with high-grade disease, compared to BRCA2 P/LP variant positive patients and with sporadic/non-hereditary cases of breast cancer." (PMID 35710434, 2022). "We developed a Bayesian network model of a hypothetical cohort of carriers of BRCA1 or BRCA2 diagnosed with stage I/II unilateral breast cancer and treated with breast-conserving treatment who underwent subsequent second primary cancer risk–reducing strategies." (PMID 36580360, 2022). "Pearson’s correlation and Spearman’s correlation analyses were performed for the three groups of breast cancer patients, i.e., BRCA1-mutated, BRCA2-mutated, and ErbB2-amplified breast cancer patients, depending on the normal or non-normal distribution of expression data." (PMID 35740092, 2022). "Majority of inherited breast cancer is associated with BRCA1 and BRCA2." (PMID 36268285, 2022). "In approximately 70 and 23% of breast cancers, BRCA1 and BRCA2 mutations have been reported." (PMID 35145999, 2022). "The lifetime risk of breast cancer in carriers of BRCA1 and BRCA2 mutations is 45–80%." (PMID 35744786, 2022). "Most carriers of BRCA1 and BRCA2 with luminal breast cancer in stage I benefited from RRBM-RRBSO." (PMID 36580360, 2022). "The variants detected in the present study were not among the most frequent mutations in BRCA1 and BRCA2 in Brazilian patients with breast cancer." (PMID 34287479, 2021). "Overall, these findings provide a mechanism that includes interactions among excess body fat, inflammation, metabolic dysfunction, and aromatase in the breast that help to explain why excess body fat is likely to increase the penetrance of breast cancer in BRCA1 and BRCA2 mutation carriers." (PMID 33649363, 2021). "A breast cancer 2 (BRCA2) positive woman with NF1 and chronic lymphocytic leukemia is described." (PMID 33954070, 2021).